SHLD2 (shieldin complex subunit 2)
Description:
Component of the shieldin complex, which plays an important role in repair of DNA double-stranded breaks (DSBs). During G1 and S phase of the cell cycle, the complex functions downstream of TP53BP1 to promote non-homologous end joining (NHEJ) and suppress DNA end resection. Mediates various NHEJ-dependent processes including immunoglobulin class-switch recombination, and fusion of unprotected telomeres.
Synonyms: FAM35A; RINN2; MGC5560; bA163M19.1; FAM35A1
Tractability: Small molecule: a structure with a bound ligand is known. PROTAC: ubiquitination databases record sites on it.
Gene: Protein-coding gene on chromosome 10 (87,094,006 to 87,191,478, forward strand). Ensembl gene ENSG00000122376.
Subcellular location: Nucleus; Chromosome
Subcellular location (Human Protein Atlas): Nucleoplasm; Actin filaments
Gene Ontology:
Molecular function: protein binding
Biological process: negative regulation of double-strand break repair via homologous recombination; positive regulation of double-strand break repair via nonhomologous end joining; positive regulation of isotype switching; regulation of double-strand break repair via homologous recombination; somatic diversification of immunoglobulins involved in immune response; telomere maintenance in response to DNA damage
Cellular component: chromosome; nucleoplasm; nucleus; site of double-strand break; chromatin
Genetic constraint (gnomAD): Loss-of-function variants: 28 observed, 58.16 expected, observed/expected ratio (o/e) 0.48, 90% interval 0.36 to 0.66. The synonymous counts are far from expectation, so gnomAD's model fits this gene poorly and the ratio says little. Missense variants: 664 observed, 879.39 expected, observed/expected ratio (o/e) 0.76, 90% interval 0.71 to 0.81. Synonymous variants: 245 observed, 308.98 expected, observed/expected ratio (o/e) 0.79, 90% interval 0.71 to 0.88.
Homologues: Orthologues: macaque SHLD2 (91% identical), chimpanzee SHLD2 (76% identical), pig SHLD2 (73% identical), dog SHLD2 (69% identical), mouse Shld2 (65% identical), rat Shld2 (64% identical), rabbit SHLD2 (62% identical), guinea pig SHLD2 (56% identical), tropical clawed frog shld2 (35% identical), zebrafish shld2 (28% identical).
Diseases named in the same sentence as SHLD2 in open-access papers:
SHLD2 is named in the same sentence as 14 diseases in open-access papers, as found by Europe PMC text mining. Sharing a sentence is not in itself a finding about the gene and the disease. The quoted sentences say what the papers report.
breast cancer (5 papers, 2018 to 2024). A primary or metastatic malignant neoplasm involving the breast. "To further investigate this possibility in cells with a naturally-occurring pathogenic BRCA1 mutation, we generated two independent SHLD2 knockout clones (G1 and D1) from BRCA1 mutant MDA-MB-436 breast cancer cells." (PMID 34140467, 2021). "Next, we employed the breast cancer MCF‐7 cell line to study the impact of SHLD2 depletion on survival following DSB induction by IR." (PMID 30154076, 2018). "We sought to determine whether SHLD2 may contribute to the outcome of BC by interrogating two distinct patient‐based cohorts of triple negative breast cancer (TNBC) and basal‐like BC." (PMID 30154076, 2018).
prostate carcinoma (2 papers, 2018 to 2026). A carcinoma that arises from epithelial cells of the prostate gland. "We found that SHLD2 is deleted in a subset of human prostate cancers, frequently alongside PTEN loss, an adverse prognostic factor." (PMID 42284420, 2026).
glioblastoma (1 paper, 2023). The most malignant astrocytic tumor (WHO grade IV). "Although the distance between PARG and SHLD2 is longer in the human genome (37 versus 2 MB), both genes are located on chromosome 10q, and recurrent arm-level deletions in this region have been reported in multiple cancer types, such as lymphomas, glioblastoma, and lung cancer." (PMID 37209095, 2023).
melanoma (1 paper, 2021). A malignant, usually aggressive tumor composed of atypical, neoplastic melanocytes. "We also noted that SHLD2 flanks the PTEN gene on chromosome 10 and appears to be collaterally lost when PTEN is deleted in melanomas and in cancers of the breast or prostate." (PMID 34140467, 2021).
tumor (7 papers, 2021 to 2024). "ART899 is a deuterated form of ART812, the ART558 derivate shown to have efficacy in BRCA1/SHLD2-deficient tumor xenograft studies." (PMID 36689546, 2023). "The identification of three cases with germline BRCA1 mutations with somatic SHLD2 mutations in post-PARPi tumour samples suggests that through loss of the Shieldin complex, cells are diverted from NHEJ, restoring homologous recombination, leading to resistance." (PMID 38072854, 2023). "Dosing of rats bearing established MDA-MB-436 BRCA1/SHLD2 defective tumours with ART812 resulted in significant tumour inhibition and was well-tolerated." (PMID 34140467, 2021). "The observation that SHLD2 or MAD2L2 siRNAs caused sensitivity to ART558 in a BRCA1 mutant cell line raised the possibility that a Polθ inhibitor could be used to target PARP inhibitor resistance caused by Shieldin complex defects when these occur in BRCA1 mutant tumour cells." (PMID 34140467, 2021). "In support of this, CRISPR-Cas9-mediated inactivation of SHLD2 did not drive resistance in cultured KB2P tumor cells." (PMID 37209095, 2023). "As MDA-MB-436 cells could be established as tumour xenografts in rats, we assessed the ability of a Polθ inhibitor to target established BRCA1/SHLD2 defective tumours in vivo." (PMID 34140467, 2021).
cancer (5 papers, 2018 to 2024). A tumor composed of atypical neoplastic, often pleomorphic cells that invade other tissues. "In conclusion, our study proposes a mechanistic model that USP25 deubiquitinates and modifies SHLD2 with K63‐linked polyubiquitin chains at the K64 site, thereby promoting NHEJ repair, which in turn decreases chemosensitivity in cancer cells." (PMID 38803048, 2024). "Overall, these findings reveal USP25 as a critical effector of SHLD2 in regulating the NHEJ repair pathway and suggest its potential as a therapeutic target for cancer therapy." (PMID 38803048, 2024). "Recent studies have shown that, in human cancer cells, the tetrameric Shieldin complex (comprising REV7, SHLD1, SHLD2, and SHLD3) facilitates non-homologous end-joining (NHEJ) while blocking homologous recombination (HR)." (PMID 39630591, 2024).
SHLD2 also shares sentences with these, for which no sentence is quoted: gout (7 papers); hyperuricemia (2); colon cancer (1); lung carcinoma (1); lymphoma (1); ovarian carcinoma (1); serous ovarian cancers (1); triple-negative breast carcinoma (1).